CTF1 (cardiotrophin 1)
Description:
Functions as a cytokine that binds to the LIF receptor complex. The LIF receptor complex indeed consists of two signaling receptor subunits IL6ST/gp130 and LIFR that transduce the signal into the cell (By similarity). Functionnally, acts as a potent cardiac survival factor, and promotes cardiomyocyte proliferation and hypertrophy. Mechanistically, ligand binding to LIFR, induces heterodimerization with IL6ST/gp130 activating JAK tyrosine kinases (JAK1 or JAK2 and to a lesser extent TYK2) bound to their intracellular domains (By similarity). These kinases subsequently phosphorylate IL6ST/gp130 and LIFR (By similarity). The tyrosine phosphorylated signaling receptors serve in turn as docking sites for recruitment and activation of signal transducer and activator of transcription STAT3 (By similarity).
Synonyms: CT-1; CT1
Tractability: Antibody: its Gene Ontology location is reachable by antibodies, with high confidence; UniProt places it where antibodies can reach, with medium confidence.
Gene: Protein-coding gene on chromosome 16 (30,896,614 to 30,903,547, forward strand). Ensembl gene ENSG00000150281.
Subcellular location: Secreted
Pathways (Reactome):
Immune System: IL-6-type cytokine receptor ligand interactions
Gene Ontology:
Molecular function: protein binding; cytokine activity; leukemia inhibitory factor receptor binding
Biological process: oncostatin-M-mediated signaling pathway; positive regulation of tyrosine phosphorylation of STAT protein; cell surface receptor signaling pathway via JAK-STAT; cell-cell signaling; muscle organ development; nervous system development; neuron differentiation; positive regulation of cell population proliferation; cardiac muscle cell apoptotic process; cardiac muscle hypertrophy
Cellular component: extracellular region
Genetic constraint (gnomAD): Loss-of-function variants: 12 observed, 6.69 expected, observed/expected ratio (o/e) 1.79, 90% interval 1.06 to 1.96. That is too few expected variants to judge how well the gene tolerates losing a copy. Missense variants: 254 observed, 173.21 expected, observed/expected ratio (o/e) 1.47, 90% interval 1.32 to 1.63. Synonymous variants: 133 observed, 88.56 expected, observed/expected ratio (o/e) 1.5, 90% interval 1.3 to 1.73.
Gene-disease validity (ClinGen):
ClinGen rates the evidence that CTF1 causes each of these diseases.
dilated cardiomyopathy (autosomal dominant): Limited. Cardiomyopathy which is characterized by dilation and contractile dysfunction of the left and right ventricles.
Homologues: Orthologues: chimpanzee CTF1 (99% identical), macaque CTF1 (93% identical), dog CTF1 (85% identical), pig CTF1 (80% identical), mouse Ctf1 (79% identical), rat Ctf1 (75% identical), rabbit CTF1 (63% identical). Paralogues in human: CLCF1 (21% identical).